BRCA1 (BRCA1 DNA repair associated)
Diseases named in the same sentence as BRCA1 in open-access papers (continued):
Sharing a sentence is not in itself a finding about the gene and the disease.
cervical cancer (continued). "The P/LP variants in BRCA1 (OR, 4.92; 95% CI, 1.22-14.68; P = .01) and BRCA2 (OR, 4.46; 95% CI, 1.11-13.14; P = .02) were associated with cervical cancer." (PMID 37523182, 2023). "The most common cancers in female relatives of BRCA1 carriers were breast (33.0%), ovarian (11.5%), and liver (3.8%) cancers, followed by lung and cervical cancers (2.4% each)." (PMID 36861435, 2023). "The results presented here show that the increased expression of CHEK2 and BRCA1 is a common event in the natural history of cervical cancer." (PMID 35745491, 2022). "In cervical cancer, the activated GPR81 can enhance the expression levels of DNA repair proteins for improving the efficiency of DNA repair, including breast cancer type 1 susceptibility protein (BRCA1), Nijmegen breakage syndrome 1 (NBS1), and DNA-PKcs." (PMID 36612084, 2022). "An investigative group which performed theranostic evaluation of cervical cancer specimens demonstrated that 21% of tumors had BRCA2 mutations and 10% had BRCA1 mutations." (PMID 36330376, 2022). "In the current study, we investigated the prognostic relevance of expression of BRCA1 in cervical cancer by IHC analysis of BRCA1 in cervical cancer tissue for comparison of overall survival according to BRCA1 expression." (PMID 34820332, 2021). "A method for identifying BRCA1 expression would be useful for prognostication of cervical cancer patients." (PMID 34820332, 2021). "In conclusion, low expression of BRCA1 in cervical cancer has potential prognostic and therapeutic significance." (PMID 34820332, 2021). "PMS1, RAD54B, FAAP20 and BRCA1 exhibited almost uniform hyper- or hypomethylation in the cervical cancer samples." (PMID 27683114, 2016). "In this study, we showed that BRCA1 and BRCA2 overexpression in patients with advanced cervical cancer is associated with treatment failure." (PMID 24708616, 2014). "Validation of the gene using real-time PCR showed a 9.2-fold increase in BRCA1 expression in cervical cancer as compared to normal cervix." (PMID 24403257, 2013). "The study also identified novel genes of significance; for instance, the DNA repair gene-BRCA1 expression was found to be upregulated in cervical cancer as compared to normal cervix in this study." (PMID 24403257, 2013). "Moreover, etoposide-induced BRCA1 promoter activity in cervical cancer cells was mediated by upregulated EGR1, which confirms the link between EGR1 and DNA damage repair." (PMID 38467631, 2024). "Furthermore, the risks for liver (RR = 3.73, 95% CI = 1.84-7.58; P = 0.002) and cervical cancers (RR = 2.99, 95% CI = 1.22-7.31; P = 0.030) in female relatives of BRCA1 carriers were significantly higher than female relatives of non-carriers." (PMID 36861435, 2023). "In addition, we also found that the risks for liver and cervical cancers in female relatives of BRCA1 carriers, and lymphoma and kidney cancer in female relatives of BRCA2 carriers were significantly increased compared with female relatives of non-carriers." (PMID 36861435, 2023). "However, studies on genomic profiles of cervical cancer patients regarding BRCA1 expression are insufficient." (PMID 34820332, 2021). "In this study, we performed BRCA1 expression analysis using immunohistochemistry (IHC), an inexpensive and widely available technique, in cervical cancer patients for its prognostic significance, and determined the correlation between its mRNA and protein expression." (PMID 34820332, 2021). "We performed immunohistochemistry staining for BRCA1 using cervical cancer tissues." (PMID 34820332, 2021).
cervical cancer (continued). "Genes with known or likely deleterious variants among cervical cancer patients with DDR gene alterations were ATM (n = 3, 2.33%), BRCA2 (n = 3, 2.33%), ATR (n = 2, 1.55%), CHEK2 (n = 2, 1.55%), followed by BRCA1 (n = 1, 0.78%), FANCA (n = 1, 0.78%), MSH6 (n = 1, 0.78%), and RAD51D (n = 1, 0.78%)." (PMID 35071000, 2021). "Further studies with larger sample sizes are warranted to determine whether BRCA1 expression is an important prognostic factor that determines poor response to radiation and chemotherapy for subgroups of patients with cervical cancer." (PMID 34820332, 2021). "Although there are some targeted drugs that may be effective for cervical cancer, such as PARP inhibitors (for BRCA1 or BRCA2 mutations patients), EGFR tyrosine kinase inhibitors (for EGFR mutations patients), gene detection is still not widely used in China." (PMID 32265980, 2020). "BRCA1, ESR1, PCNA, and FGFR2 have already been shown to be associated with cervical cancer." (PMID 30020984, 2018). "Documentation of frequent mutations in BRCA1 and BRCA2 as well as in vitro efficacy against cervical cancer cells grants biological plausibility to the targeted treatment of cervical cancer with PARP-inhibitors, as well as for routine tumor genomic assessment of cervical cancer specimens." (PMID 36330376, 2022). "Hypermethylation of the BRCA1 promoter was observed in advanced stage invasive cervical cancer patients.Another study reported that BRCA1 promoter methylation may be related to worse prognosis since patients carrying this mutation failed to respond to the treatment." (PMID 29312619, 2017). "For this purpose, T47D (BC cell line, BRCA1 and BRCA2 wt., HRP) and HeLa cells (cervical cancer cell line, BRCA1 and BRCA2 wt., HRP) were treated with a combination of curcumin (10, 20, and 30 μM) and the PARPi olaparib (0.1 and 0.25 μM)." (PMID 40647408, 2025). "Expression of the DNA repair enzymes BRCA1/2, PALB2, and RAD51 were increased in cancer samples compared to controls, indicating that double-stranded DNA repair activity increases during cervical cancer progression." (PMID 39672307, 2024). "Overall, we observed higher mRNA levels of CHEK2 and BRCA1 genes in CIN and cervical cancer samples when compared to normal cervix tissue." (PMID 35745491, 2022). "We show that the down-regulation of ATM, BRCA1, and CHEK2 genes expression selectively affected HPV-positive cervical cancer-derived cells proliferation/viability." (PMID 35745491, 2022). "RPP25, BARD1, BRCA1, CD3EAP, CSTF2, DARS2 and DNMT3B was up-regulated in most of cervical cancer tissues compared with corresponding normal cervix tissues." (PMID 34863153, 2021). "Prostate (PC3) and cervical carcinoma (HELA) cell lines experienced lowered viability and cell cycle arrest at G2/M after BRCA1 knockdown, but continued growing." (PMID 27845331, 2016). "Three mutational markers (TNFAIP3, BRCA1, ASXL1) of non-responders were found to be shared with the DNA markers from patients with progressive disease in an independent cervical cancer cohort (GEO repository: GSE205247)." (PMID 38951894, 2024). "In cervical cancer, we also identified LOH in 28.6% (2 of 7) of BRCA1/2 and 11.1% (1 of 9) of non-BRCA HRR germline-variant tumors." (PMID 37523182, 2023). "We identified that inhibition of the ATM/CHK2/BRCA1 axis selectively affects the proliferation of cervical cancer-derived cell lines, without altering normal primary human keratinocytes (PHK) growth." (PMID 35745491, 2022). "Herein, we demonstrate active and on demand targeting of TET1CD to the BRCA1 promoter region using a CRISPR/dCas9 platform in order to decrease DNA methylation, re-activate gene expression and to restore BRCA1 functional activity in breast and cervical cancer." (PMID 27356740, 2016).
cervical cancer (continued). "DNA repair pathway genes, such as BRCA1, BRCA2 and ATM, which are potential predictive biomarkers, also had a high frequency of CNVs in the present study, suggesting that HR defect might serve as a therapeutic target in cervical cancer." (PMID 35205332, 2022). "Second, although the relationship between IHC results and prognosis was shown, a comparative NGS study was not conducted to determine whether gene expression in cervical cancer was consistent with the BRCA1 IHC results." (PMID 34820332, 2021). "The ‘Role of BRCA1 in DNA Damage Response’ was predicted to be the most significantly activated canonical pathway (p = 1.86E-04), which suggests a baseline intrinsic resistance of non-responding cervical cancer tumors." (PMID 24708616, 2014). "Immunohistological staining confirmed increased expression of BRCA1, BRIP1, FANCD2 and RAD51 in non-responsive compared with responsive advanced squamous cervical cancer, both in the initial set of 21 cervical cancer samples and the second set of 24 samples." (PMID 24708616, 2014). "The overexpression of BRCA1, BRCA2, RAD51, BRIP1 (BACH1), FANCD2, BLM and RFC in non-responding versus responding cervical cancer samples suggests that DNA repair mechanism activation occurs through cell cycle arrest and homologous recombination." (PMID 24708616, 2014).
metastatic disease (59 papers, 2011 to 2026). "This is in contrast to BRCA1 with only one somatic variant and one germline PV in metastatic disease (1/338) found in combination with a gATM PV." (PMID 40046829, 2025). "Extensive analyses have revealed that somatic BRCA1 mutations are uncommon in unselected patients, but they can be important targetable mutations in metastatic disease." (PMID 38540206, 2024). "Raw IHC scores, which were the average scores from the quantity and intensity of staining, were plotted for primary and metastatic tumor samples, stratified into WT, BRCA1-mutated and BRCA2-mutated groups." (PMID 38943334, 2024). "The RAD18 IHC scores were significantly higher in the BRCA1-mutated primary and metastatic tumor samples, relative to WT tumors." (PMID 38943334, 2024). "The guidelines of the European Association of Urology and National Comprehensive Cancer Network recommend BRCA1/2 testing for PCa patients with positive family history, high-risk or very high-risk localized or metastatic disease." (PMID 36509931, 2023). "This is in accordance with current EAU and NCCN guidelines recommending BRCA1/2 testing for PCa patients with high-risk and very high-risk localized or metastatic disease or for those with positive family history." (PMID 36509931, 2023). "We previously analyzed our tissue NGS datasets and publicly available mPC datasets, concluding that BRCA1/2-mutated metastatic tumors differ from wild-type tumors in PSA levels at diagnosis." (PMID 37568814, 2023). "Namely, the frequency of somatic BRCA1/2 mutations is 10.94% in patients with metastatic disease (11.26% when the analysis is limited to the castration-resistant setting) and 7.18% in all patients with any stage PC." (PMID 37173901, 2023). "Retrospective data on high-dose chemotherapy deserve consideration given some unexpected instances of cure from metastatic disease among BRCA1/2-mutated patients." (PMID 27555886, 2016). "There is also a number of case reports describing patients with germ-line BRCA1/2 mutations, who were treated by high-dose chemotherapy for the metastatic disease and remained tumor-free for years." (PMID 27555886, 2016). "Put differently, 17 (73%) of the 23 patients with metastatic disease at presentation were positive for the BRCA1-3’UTR-variant, compared to 349 (51%) of 680 patients without metastatic lesions (p = 0.040, OR 2.7, 95% CI 1.1-6.9)." (PMID 24915755, 2014). "The BRCA1/2 carriers had a higher likelihood of having received a diagnosis of de novo metastatic disease compared with patients with tumor relapsing after local therapies (43.8% vs 18.4%; P = .045)." (PMID 39982725, 2025). "The trial was the first report of PARPi response in patients with BC with somatic BRCA1/2 mutations, and now Olaparib is a category 2b NCCN (National Comprehensive Cancer Network) guideline recommendation for treatment in metastatic disease, any subtype." (PMID 38540206, 2024). "In the metastatic disease, BRCA1 was found to be methylated in 26/50 (52%) while BRCA2 was found methylated in 23/50 (46%)." (PMID 38577595, 2024). "In patients with metastatic diseases, germline BRCA1/2 genotyping should probably be initiated early when the endocrine therapy combined with CDK4/6 inhibitor is started." (PMID 35158866, 2022). "Our Gene Ontology (GO) analysis of the enrichment of genes in biological process with RNA expression files from mammary glands and primary and metastatic tumors in Brca1-MSK and WT mice revealed that fatty acid metabolic processes were highly activated." (PMID 35025764, 2022). "The inclusion of germline genetic testing for variants in genes such as BRCA1/2, ATM and CHEK2 are likely to be incorporated into mainstream testing for men presenting with locally advanced or metastatic disease." (PMID 33486571, 2022).
metastatic disease (continued). "Priority genes to test for metastatic disease treatment included BRCA1, BRCA2, and dMMR genes, whereas broader testing such as ATM is reserved for clinical trial eligibility." (PMID 33801751, 2021). "In a study of 2000 patients with localized prostate cancer, including BRCA1 and BRCA2 mutation carriers, 23% of the mutation carriers developed metastatic disease five years after radical treatment." (PMID 34884434, 2021). "Considering these results, reappraisal of the predictive value of BRCA1 promoter methylation status prior to the initiation of CT for metastatic disease appears necessary." (PMID 32235500, 2020). "For BRCA1/2m carriers with metastatic disease and fewer than two chemotherapy regimens in the metastatic setting, use of the PARPi olaparib results in a significantly longer PFS and better quality of life than standard chemotherapy." (PMID 29867226, 2018). "BRCA1 was expressed in all primary and metastatic tumors with strong staining in 71% (25/35) of primary tumors and 82.4% (14/17) of metastatic tumors." (PMID 24904527, 2014). "Germlime mutations of BRCA-1 and -2 genes have been reported in 10% of EOC and they seem to correlate with a more aggressive behaviour and a metastatic disease." (PMID 25069863, 2014). "It is possible that loss of BRCA/p220 combined with BRCA1-IRIS overexpression generates much more aggressive, invasive, and/or metastatic tumors." (PMID 22511931, 2012). "Similarly, PARP inhibitors such as Olaparib and Talazoparib target deficient DNA repair in germline-associated BRCA1/2-mutated, HER2-negative metastatic disease." (PMID 41154364, 2025). "According to the guidelines from the Society of Surgical Oncology (ASCO), all patients newly diagnosed with BC at stages I-III or with de novo stage IV/metastatic disease who are 65 years or younger should be offered BRCA1/2 testing (Formal Consensus; Agreement: 87.5%)." (PMID 39057154, 2024). "Our tumor collection recapitulates BRCA1/2 loss-driven tumor formation and acquired PARPi resistance but does not capture the full complexity of the human cancer (e.g., metastatic disease, heterogeneity, hypomorphic mutations)." (PMID 37209095, 2023). "Loss of function of BRCA1/2, ATM (a DNA-damage checkpoint indirectly activating HRR), and other HRR genes are associated with more aggressive PCs (higher Gleason score; lymph node involvement, and/or metastatic disease at presentation; worse CSS/MFS)." (PMID 35203446, 2022). "In the analyzed cohort with metastatic disease, the survival did not depend on the BRCA1/2 mutation status." (PMID 32322271, 2020). "Evidence regarding the use of BRCA status or homologous recombination competency to guide treatment selection in BC is strongest in the setting of metastatic disease, and several recent clinical studies have evaluated platinum salts and PARPi in patients with advanced or metastatic BC and BRCA1/2m." (PMID 29867226, 2018). "Further assessment of PPC risk after RRBSO in BRCA1/2 PV carriers where STIC lesions were identified may justify some sort of an intervention, such as staging CT scan to exclude metastatic disease or even a course of PARP inhibitor treatment if substantial rates continue to be reported." (PMID 33152107, 2021). "Moreover, denosumab is currently used to treat bone fractures of metastatic disease and RANKL inhibition has been extensively studied in preclinical tumour models and is now proven as a preventive strategy for women carrying BRCA1 mutations and high risk of BC." (PMID 31181781, 2019). "In clinical practice, comprehensive genomic profiling—preferably using next-generation sequencing (NGS) panels covering BRCA1/2 and other HRR genes—should be conducted at the time of diagnosis of metastatic disease or upon progression to castration resistance." (PMID 40732303, 2025).
metastatic disease (continued). "This was further confirmed by comparing BRCA1 expression in 4T1 cells with CSCs-derived control and DOX treated metastatic tumors, as well as between lungs of tumor-bearing mice of these groups." (PMID 38796426, 2024). "Only a subset of patients with germline defects in BRCA1/2 genes can potentially benefit from personalized therapy, with the PARP inhibitor olaparib serving as a maintenance treatment for metastatic disease." (PMID 39333096, 2024). "Among them, the BRCA1 (chr17q21.31) and BRCA2 (chr13q13.1) loci were frequently amplified (CNV-gain), and most were shared between primary and metastatic tumors." (PMID 36140756, 2022). "BRCA1 and BRCA2 have been identified as increasingly frequent in advanced metastatic disease compared to primary tumors." (PMID 34884434, 2021). "BRCA1-IRIS-positive tumors were high-grade, aggressive and metastatic tumors that expressed higher levels of AKT and survivin, and lacked expression of BRCA1/p220 compared to BRCA1-IRIS-negative tumors." (PMID 22511931, 2012). "In contrast, BRCA1 is not convincing for either somatic or germline involvement in metastatic disease in our series." (PMID 40046829, 2025). "Moreover, immunohistochemical studies of USC tumors revealed high protein expression of BRCA1 and IGF1R in primary and metastatic tumors." (PMID 29922232, 2018).